EGFR (epidermal growth factor receptor)
Diseases named in the same sentence as EGFR in open-access papers (continued):
Sharing a sentence is not in itself a finding about the gene and the disease.
prostate carcinoma (continued). "9-HODE and 13-HODE can be synthesized by cyclooxygenase (COX) and 15-lipoxygenase 1(15-LOX 1) from linoleic acid, and activation of the 15-lipoxygenase 1/13(S)-HODE axis can promote prostate cancer cell growth through the epidermal growth factor receptor (EGFR) signaling pathway." (PMID 36280842, 2022). "Mechanistically, exosomal miR-146a-5p has been shown to confer prostate cancer cells metastatic abilities through EGFR/ERK pathway, downregulate BRCA1 in triple negative sporadic BCs and play a central role within the STAT/IFN signaling axis to create an immunosuppressive microenvironment." (PMID 36293478, 2022). "A cleaved domain 5 of high molecular weight kininogen (HK) is reported to bind to urokinase-type plasminogen activation receptor (uPAR) with high affinity and inhibit EGFR phosphorylation leading to significant reduction of cell migration and invasion in human prostate cancer cells." (PMID 35109816, 2022). "Intriguingly, FBXW2 was an E3 ligase for EGFR in prostate cancer." (PMID 35499593, 2022). "rhREG4 treatment enhanced EGFR phosphorylation in prostate cancer cells." (PMID 36172286, 2022). "Thus, our data uncover a novel that FBXW2 as a tumor suppressor of prostate cancer, inhibits EGFR downstream by promoting EGFR ubiquitination and degradation, resulting in repression of cell proliferation and metastasis." (PMID 35499593, 2022). "STAP-2 is also a potent regulator of EGFR activation in prostate cancer cells." (PMID 36010693, 2022). "STAP-2 enhances EGFR-mediated proliferation of DU145 human prostate cancer cells." (PMID 36410436, 2022). "However, the phosphorylation of β-catenin at residue Y333 was due to EGFR signalling; thus, identifying a novel area of interest in the study of prostate cancer research." (PMID 35204839, 2022). "A knockdown of STAP-2 may inhibit prostate cancer cell growth by synergistically inhibiting EGFR and IL6R signaling." (PMID 36010693, 2022). "Mechanistically, TGFα, a member of the epidermal growth factor (EGF) family, was shown to bind to the EGFR leading to a significant AKT activation in the late-stage prostate cancer cells, whereas stimulation of early-stage prostate cancer cells with EGF diminishes AKT activation." (PMID 34064589, 2021). "CMTM5-v1 is found to inhibit prostate cancer (PCa) cells through the EGFR signaling pathway, and the loss of CMTM5 may be involved in the occurrence and development of PCa caused by deregulated EGFR." (PMID 33585698, 2021). "Thus, natural products including berberine, quercetin, luteolin, genistein, and resveratrol suppress the activation of intrinsic tyrosine kinase and ligand-based activation in prostate cancer cells through the reduction of EGFR level." (PMID 33807174, 2021). "Note that assay used for AR-V7 detection was a highly sensitive assay, (due to a PCR pre-amplification step before qPCR reaction), while a classical PCR was used for AdnaTest® CTC detection through at least one prostate cancer-associated transcript (PSA, PSMA, or EGFR) expression." (PMID 34885125, 2021). "Prostate cancer is concerned with the overexpression of epidermal growth factor receptor." (PMID 33807174, 2021). "EGFR is overexpressed in nearly 50% of all cases of the prostate carcinomas." (PMID 34321039, 2021). "In prostate cancer, δ-catenin can stabilize EGFR to enhance EGF signaling." (PMID 34069970, 2021). "In addition, MN triggered the apoptosis of human prostate cancer cells by suppressing the EGFR/PI3K/AKT signaling pathway." (PMID 34885972, 2021).
prostate carcinoma (continued). "Targeting EGFR with inhibitors such as gefitinib, lapatinib and erlotinib has shown limited effectiveness in prostate cancer and more recent studies reveal that the extracellular release of EGFR through exosomes may be the culprit." (PMID 33801965, 2021). "In addition to the overall preferences for targeting prostate cancer‐related proteins, the screened drugs also targeted the epidermal growth factor receptor (EGFR) signaling pathway, protein degradation, DNA repair, and cell cycle‐related proteins." (PMID 34723439, 2021). "In addition, the stimulation of ADAM17 activity promotes cell migration and the TGF-α/EGFR pathway in invasive hypoxia prostate cancer cells." (PMID 34746310, 2021). "By targeting EGFR expression, miR-1231 is downregulated in prostate cancer." (PMID 34153004, 2021). "Epidermal Growth Factor Receptor is often overexpressed in advanced prostate carcinoma." (PMID 34321039, 2021). "This occurs through set up of Epidermal Growth Factor Receptor (EGFR) and Insulin Receptor (InR) dependent autocrine loops, a phenomenon that, considering human data, could be relevant for prostate cancer." (PMID 32385236, 2020). "Taken together, these data confirm our in vitro qPCR and LC–MS/MS protein expression data that FUT8 overexpression might be driving the castration-dependent EGFR regulation in prostate cancer." (PMID 32085441, 2020). "We therefore measured FOXO3A and EGFR expression in prostate cancer cell lines by IB." (PMID 33224867, 2020). "Quercetin prevents prostate cancer progression in an in vivo model by inhibiting EGFR signaling." (PMID 33426081, 2020). "After EGFR siRNA transfection, prostate cancer cell autophagy activity increased." (PMID 33055358, 2020). "In order to investigate whether FUT8 expression was colocalized with the EGFR protein in prostate cancer cells, we performed an immunofluorescence (IF) colocalization study using confocal microscopy." (PMID 32085441, 2020). "Based on our knowledge, this is the first report that describes how FUT8 in androgen-depleted condition might be driving the expression of EGFR and rescuing prostate cancer cells from depleted androgen-induced cell death." (PMID 32085441, 2020). "Among these genes, EGFR was reported to promote prostate cancer bone metastasis." (PMID 33317606, 2020). "Work in prostate cancer cells has shown that genistein treatment significantly up-regulated 33 miRNAs whereas miR-574-3p down-regulated EGFR expression by directly binding to the 3'UTR of EGFR, thereby inhibiting the malignant biological behavior of the tumor cells." (PMID 32276266, 2020). "WFDC2, which may serve as a potential clinical treatment target of PCa, suppressed prostate cancer metastasis by inactivating EGFR signaling." (PMID 32678075, 2020). "Next, we measured LXR-α and EGFR expression status in prostate cancer tissues by IHC staining." (PMID 33224867, 2020). "C4-2B (metastatic derivative of LNCaP) prostate cancer cells pretreated with curcumin had lower levels of ligand-mediated epidermal growth factor receptor (EGFR) autophosphorylation when compared to the control, consequently hindering the EGFR ligand from promoting downstream signaling." (PMID 33182828, 2020). "Based on our knowledge, this is the first report that describes how FUT8 in an androgen-depleted condition might be driving the expression of EGFR and rescuing prostate cancer cells from depleted androgen-induced cell death." (PMID 32085441, 2020). "Notably, the results showed that EGF can significantly rescue HE4 mediated the prostate cancer metastasis suppression, which is consistent with the effect of EGFR overexpressed." (PMID 32678075, 2020). "Combined carmustine and selenite treatment significantly inhibited the transmission and proliferation of epidermal growth factor receptor signals and induced apoptosis in androgen-independent prostate cancer cells, suggesting their potential in castration-resistant prostate cancer therapy." (PMID 31531348, 2019).
prostate carcinoma (continued). "Moreover, γ-T3-induced apoptosis was also found to be associated with the suppression of NF-κB, epidermal growth factor receptor (EGFR), and Id family proteins (Id1 and Id3) in prostate cancer." (PMID 30866453, 2019). "As several studies recently revealed mechanical regulations of receptor tyrosine kinase (RTK), including EGFR signaling in cancers, these together imply roles of EGFR dynamics in advanced malignancy in prostate cancer and their potential as biophysical markers for this disease." (PMID 31805710, 2019). "In addition, we demonstrated that EGFR dynamics in advanced prostate cancer cells is tightly modulated by cortical actin organization, and the reorganization of actin networks is coordinating with cell migration and invasion." (PMID 31805710, 2019). "Moreover, overexpression of USP39 predicts poor prognosis and promotes tumorigenesis of prostate cancer via promoting epidermal growth factor receptor (EGFR) mRNA maturation and transcription elongation." (PMID 30898977, 2019). "Our studies provide a novel and testable hypothesis that connects ETV6-TWIST1 signaling to EGFR-TKI resistance during prostate cancer progression." (PMID 29455655, 2018). "Moreover, GPCRs expressed and/or overexpressed in prostate cancer are able to engage a cooperative crosstalk with growth factor receptors such as epidermal growth factor receptor (EGFR)." (PMID 30319552, 2018). "Prostate cancer still at earlier or hormone-sensitive stages containing intact ETV6 activity could be responsive to EGFR-targeted antagonists as monotherapy." (PMID 29455655, 2018). "In addition, we previously reported that activation of EGFR signaling facilitates bone metastasis of prostate cancer through EGFR-mediated transcriptional suppression of microRNA-1 (miR-1)." (PMID 29455655, 2018). "Lee also reported magnolol inhibits EGFR-mediated signaling pathways in prostate cancer." (PMID 29892225, 2018). "Because SPINK1 partially exhibits its neoplastic effects through its interaction with EGFR, EGFR inhibitors may be a potential targeted therapy for SPINK1-overexpressing prostatic cancers." (PMID 29581876, 2018). "Since resistance to EGFR antagonists eventually develops and remains a challenging phenomenon, it is possible that loss of ETV6 function promotes the development of drug resistance in prostate cancer." (PMID 29455655, 2018). "Thus, we conclude that SCIN promotes prostate cancer cell survival by stabilising EGFR and MEK/ERK signalling." (PMID 29744289, 2018). "Furthermore, the EGFR-induced enhancement of the self-renewal capacity in prostate cancer cells correlates with an upregulation of Sox2." (PMID 29401647, 2018). "The reason that C1GALT1 exhibits different effects on EGFR in prostate cancer and HNSCC cells could be due to cell-specific differential O-glycosites on EGFR." (PMID 29930379, 2018). "Furthermore, EGFR stability was meditated by SGEF through inhibited EGFR trafficking promoting prostate cancer cell progression." (PMID 29454349, 2018). "Furthermore, many EGFR-positive cancers, such as prostate cancer and ovarian cancer, are innately resistant to TKI5,6." (PMID 29358623, 2018). "However, although EGFR overexpression and EGF signaling constitutive activation in prostate cancer are associated with poor prognosis, the exact role played by EGF/EGFR in the progression and development of this disease still needs to be elucidated." (PMID 28430640, 2017). "Taken together, our study identified c-Met, CREB1, EGFR and miR-493-5p establish a regulatory loop in prostate cancer, which could prove useful in the development of effective and therapies against prostate cancer." (PMID 29137265, 2017). "Interestingly, in androgen-sensitive prostate cancer cell lines deprived of androgen, we observed a decrease in total EGFR protein expression." (PMID 28596572, 2017). "We performed Transewell assays to identify the function of EGFR in prostate cancer cell motility." (PMID 29137265, 2017).
prostate carcinoma (continued). "In prostate cancer, PTEN expression is associated with EGFR inhibitor sensitivity." (PMID 28134774, 2017). "Furthermore, we identified c-Met, CREB1, EGFR and miR-493-5p establish a regulatory loop in prostate cancer." (PMID 29137265, 2017). "However, following the binding to EGF receptor (EGFR), it stimulates cellular growth, vitality, migration and metastatic abilities of different tumors, including prostate cancer." (PMID 28430640, 2017). "This molecule was tested on epidermoid and prostate cancer cells known to express amplification of EGFR, and proved to be highly active in vitro with IC50 (inhibitory concentration: 50% inhibition) lower than 1ng/ml and doubling the mouse survival time in murine xenograft models." (PMID 27153091, 2016). "We therefore examined the surface EGFR expression levels in the prognostic and therapeutic value of CTCs before docetaxel chemotherapy in a population of bone-metastatic castration-resistant prostate cancer (mCRPC) patients at Kyorin University." (PMID 27916908, 2016). "EGFR inhibition enhances sensitivity to taxol in prostate cancer cells." (PMID 26863629, 2016). "Targeting the EGFR axis is a potential therapeutic strategy in prostate cancer." (PMID 27611943, 2016). "Furthermore, it has been demonstrated that expression of EGFR is enhanced in hormone refractory prostate cancer." (PMID 26883159, 2016). "Thus, an inverse correlation between endogenous ZNF216 and EGFR level of expression was observed in these cell lines and is in accordance with those shown in prostate cancer cell lines." (PMID 27732953, 2016). "Hyperactivity of EGFR is related to androgen independence of prostate cancer cells." (PMID 27916908, 2016). "Moreover, overexpression of AGK transactivates the epidermal growth factor receptor (EGFR) and increases prostate cancer cell migration in vitro." (PMID 26443540, 2016). "Inhibition of EGFR signaling is an effective strategy for prostate cancer treatment." (PMID 27927199, 2016). "Additionally, epidermal growth factor receptor (EGFR) transactivation has been reported in NTS-stimulated prostatic cancer cell." (PMID 25644759, 2015). "Interestingly, in prostate cancer cells, researchers found that EGFR induced mitochondrial fusion through upregulation of OPA1 and involve in de novo synthesis of the fatty acid, palmitate." (PMID 26497368, 2015). "Nevertheless, a prognostic/diagnostic role of EpCAM in EGFR activated prostate cancer cells should not be ruled out." (PMID 25967040, 2015). "However, the few clinical trials in prostate cancer using drugs targeting Epidermal Growth Factor Receptor (EGFR), VEGFR-2 and HER2 were discouraging so far." (PMID 25894226, 2015). "Moreover, enhanced expression of EGFR and the subsequent increase in ERK and AKT signaling have been implicated in the progression of prostate cancer." (PMID 25652422, 2015). "The EGFR pathway has been found to play important roles in tumorigenesis and development, and EGFR overexpression has been observed in many epithelial cancers, including lung, breast, colon, and prostate cancers." (PMID 25679210, 2015). "Furthermore, in a recent study that compared EGFR-mutated and EGFR-wild type tumors, ANXA3 was identified as one of only four downregulated genes involved in prostate cancer progression." (PMID 26475168, 2015). "Also noteworthy is SOS1, a regulator of EGFR expression and downstream signaling, which also shows increased expression in African American prostate cancer patients." (PMID 25802834, 2015). "Importantly, inhibition of miR-203 induced both cell invasion and resistance to TKIs treatment in prostate cancer cells, implying a dominant biological function for miR-203 in the EGFR network." (PMID 25004126, 2014).
prostate carcinoma (continued). "Wnt ligand is reported to trigger proliferation through extracellular signal-related kinases (ERKs, the classical MAPKs) in fibroblasts, and β-catenin can induce epidermal growth factor receptor (EGFR) gene expression in hepatocellular and prostate carcinoma cells." (PMID 24816560, 2014). "Interestingly, it has been reported that AGK overexpression promotes aggressiveness in prostate cancer cells through activation of EGFR, and that upregulation of AGK promotes the stem cell-like phenotype in ESCC by sustaining JAK2 activity." (PMID 24886245, 2014). "Although Ras mutation in prostate cancer varies between populations, we hypothesized that persistent RAS activity might explain the induction of the EGFR signaling pathway in advanced prostate cancer cells." (PMID 25004126, 2014). "In prostate cancer, EGFR is elevated along with disease progression." (PMID 24741584, 2014). "The role of miR-203 in Ras-activated metastasis and EGFR inhibitor resistance in prostate cancer tumors remains largely unknown." (PMID 25004126, 2014). "The overexpression of EGFR has been shown in a majority of cases of prostate cancer." (PMID 25004126, 2014). "It was also found that prostate cancer bone metastases express significantly higher level of EGFR." (PMID 24741584, 2014). "Furthermore, it has been shown that 100% of metastatic, castration-resistant prostate cancers (CRPC) express EGFR, suggesting that EGFR signaling plays an important role in the progression of prostate cancer." (PMID 25004126, 2014). "However, it is unclear how miR-203 modulates EGFR signaling and how miR-203 regulates the expression of EGFR signaling-related genes in Ras-activated prostate cancer metastasis." (PMID 25004126, 2014). "ErbB-related pathways were identified in the metastatic network, including the ErbB network pathway, ErbB4 pathway, Her2 pathway, ErbB2/ErbB3 signaling pathway and the EGFR pathway, which are implicated in prostate cancer progression and metastasis." (PMID 23782521, 2013). "In conclusion, our observations indicated targeting AR, PI3K/Akt, Bcl-2, Src, and EGFR signaling pathway may be a choice for treatment of castration-resistant AR-positive prostate cancers." (PMID 24349321, 2013). "Recently, it has been reported that a disintegrin and metalloprotease 17 (ADAM17) could induce prostate cancer cell proliferation via EGFR/PI3K/Akt pathway activation." (PMID 24311896, 2013). "ANXA3 was identified as one of the four down-regulated genes involved in prostate cancer progression in a recent study that compared EGFR mutated and non-mutated tumours." (PMID 23555683, 2013). "Moreover, the EGFR inhibitor gefitinib is ineffective in treating hormone-refractory prostate cancer, a result questioning the significance of the EGFR/HER2 axis in the molecular pathogenesis of prostate cancer." (PMID 22991510, 2012). "Moreover, changes in the proliferative epidermal growth factor receptor (EGFR) pathway influence the response to androgen deprivation therapy (in advanced cases of the prostate cancer) and can modulate cancer progression in different cancer models." (PMID 23233863, 2012). "Nonetheless, crosstalk between the AR and EGFR pathways remains unclear in bladder cancer, although it has been widely studied in prostate cancer." (PMID 22922989, 2012). "Despite significant advances in our understanding of the mechanism of action of Id1 in prostate cancer, such as regulation of p16, EGFR, androgen independence, prostate-specific antigen expression and its role in cell proliferation and metastasis, the expression Id1 has remained controversial." (PMID 23342268, 2012). "EGFR may also sensitize prostate cancer cells to low levels of androgens by enhancing co-activator binding and transcriptional activation of endogenous and ectopically expressed AR." (PMID 23185449, 2012).